CD4 (CD4 molecule)
Diseases named in the same sentence as CD4 in open-access papers (continued):
Sharing a sentence is not in itself a finding about the gene and the disease.
pneumonia (continued). "Cell-mediated immune responses, like antigen-specific Th1 and Th17 cells, mainly derived from CD4+CD8+ T cells, as well as CD8+ T cells are considered important for the protection against a Mycoplasma-induced pneumonia." (PMID 36569943, 2022). "As the number of CD4+ T lymphocytes decreases, the immunity of HIV-1 infected patients will be severely impaired, leading to complications such as pneumonia and tumors." (PMID 35368687, 2022). "Consolidation was the most common imaging chest CT finding of patients with Adv+ pneumonia, who were also revealed to harbor lower numbers of CD3+, CD4+, and CD8+ T-cells." (PMID 36161612, 2022). "Pair-wise comparisons showed that the mean CD4 counts for the HIV cohort (262 cells/mm3), pneumonia cohort (183 cells/mm3) and TB cohort (127 cells/mm3) differed significantly (t test, p = 0.007)." (PMID 35643931, 2022). "A retrospective study conducted in Taiwan indicated an inhibition of cellular immunity, as evidenced by significant reduction in counts of CD4+, CD8+, and CD20+ T-cells in patients with Adv-7 pneumonia showing pleural effusion." (PMID 36161612, 2022). "Patients with Adv+ pneumonia showed significantly lower numbers of CD3+ (p = 0.034), CD4+ (p = 0.031), and CD8+ T-cells (p < 0.004) than did those with Adv+ non-pneumonia." (PMID 36161612, 2022). "In our current study, we identified DNT and CD4+ TCM expressed increased Lag3 and Tim3 in acute pneumonia and stable pneumonia." (PMID 34841705, 2021). "Clusters 09 and 16, which identified to be DNT and CD4+ TCM, respectively, significantly increased in patients with acute pneumonia and stable pneumonia with an enhanced expression of Lag3 and Tim3, which were identified to be the exhausted clusters." (PMID 34841705, 2021). "In contrast to post-CLP, AM from post-pneumonia mice expressed high MHC-II, a defence-ready transcriptomic signature and promoted antigen-specific CD4 T cells proliferation." (PMID 34185186, 2021). "Compared to the group with mild/moderate pneumonia, children with severe pneumonia had an increased count of CD8+ T cell and a lower percentage of CD4+ T cell." (PMID 33937149, 2021). "The proportion of activated CD4+ T cells was decreased in patients with LC, COPD and AECOPD, while increased in pneumonia." (PMID 34841705, 2021). "Thus, it is possible that other mediating variables associated with poor viral control (e.g., cases of pneumonias) may be driving the increased NSCLC incidence among people living with HIV rather than CD4 count in well-controlled individuals living with HIV." (PMID 33348663, 2020). "Neutrophil proportion, NLR, IL-6, ESR, CRP, and procalcitonin were generally higher in the pneumonia patients than in the pneumonia-free patients, in contrast to CD8+ and CD4+ T lymphocyte counts." (PMID 33239109, 2020). "SFJDC increased the CD4+/CD8+ ratio and number of natural killer (NK) cells, thus, having a therapeutic effect in the pneumonia model." (PMID 32848729, 2020). "Compared with the stable group, the pneumonia group showed poor immune status, which was characterized by significantly lower cell counts of total T cells (CD3+ T cells), T cell subsets (CD4+ T cells and CD8+ T cells), B cells and NK cells." (PMID 32993687, 2020). "In the present study, we analyzed the separate effects of CD4+ T cell depletion and CD8+ T cell depletion on protective immunity against IAV-induced severe pneumonia model in mice immunized with HAv-SF-10." (PMID 29370185, 2018). "The results showed that in TB patients, CXCR3 expression in CD4+ and CD8+ cell subsets was lower in the lung compared to the periphery, whereas in pneumonia, the CXCR3 expression in CD4+ and CD8+ cell subsets was lower in the periphery compared to the lung." (PMID 30026741, 2018). "Previously, pneumonia was shown to be a major source of morbidity in HIV, even in patients with high CD4 cell counts." (PMID 27719675, 2016).
pneumonia (continued). "In the post-acute phase of pneumonia, PαS MSC-treated animals exhibited significantly reduced respiratory IL-17+ CD4+ T cells and IFN-γ+ CD4+ T cells." (PMID 26438075, 2015). "Mice reconstituted with CD4+CD25- T cells were able to eliminate the pathogen, but died of acute pneumonia consequent of intense infiltration of inflammatory cells." (PMID 26512987, 2015). "We evaluated the efficacy of the adoptive transfer of memory B, CD4+, and CD8+ T lymphocytes compared with sulbactam and tigecycline in an experimental murine pneumonia model by two multidrug-resistant Acinetobacter baumannii strains, colistin-susceptible AbCS01 and colistin-resistant AbCR17." (PMID 39408879, 2024). "However, opposite opinions have reported higher CD8 + T cell level and lower CD4+/CD8 + T cell ratio have been seen in children with pneumonia." (PMID 38678181, 2024). "Patients with acute ischemic stroke may suffer from immune imbalance (abnormal levels of CD3+, CD4+ and CD4+/CD8+), leading to pneumonia, intracranial edema, infection and other complications, and worsening brain injury." (PMID 36381080, 2022). "Areas under the ROC curve for CD3+, CD4+, and CD8+ T-cells were 0.8423, 0.8482, and 0.75, respectively, indicating that counts of CD3+, CD4+, and CD8+ T-cells may be used as predictors of pneumonia in Adv+ patients." (PMID 36161612, 2022). "The percentages of CD4+ T cells in three monkeys (#001, #007, and #012) for which CT imaging showed no pneumonia transiently increased, whereas CD8+ T cells decreased transiently after rechallenge with the virus." (PMID 34625475, 2021). "The double‐negative T cells and exhausted CD4+ central memory T cells subset were identified in patients with acute pneumonia." (PMID 34841705, 2021). "While we observed that antibodies participate in bacterial clearance, depletion of CD4+ T cells during WCV priming did not affect bacterial burden during acute pneumonia." (PMID 33199354, 2021). "Additionally, we observed a TLR2-dependent increase in regulatory T cells (Tregs) proportion among CD4 T cells in the lung of post-CLP mice at day 7 when compared to controls and post-pneumonia mice." (PMID 34185186, 2021). "We found that total lymphocytes, CD3+, CD4+ and CD8+ T lymphocytes significantly went down in the severe type patients compared to the common type which indicated SARS-CoV-2 can impose hard blows on human lymphocyte resulting in lethal pneumonia." (PMID 32364527, 2020). "But interestingly, consistent with their high CD4+/CD4- ratio, iNKT cells from patients who did not develop pneumonia presented a higher frequency of IL-4 positive cells." (PMID 31253189, 2019). "We observed a higher CD4+/CD4− ratio of the iNKT cells from BI patients and an even higher ratio in patients who did not develop pneumonia." (PMID 31253189, 2019). "Here, we provide evidence that while both airway and gut microbiota are perturbed in parallel in HIV-infected pneumonia patients, it is not the airway, but rather the gut microbiota that relates to peripheral CD4 cell counts." (PMID 30857553, 2019). "HCV coinfection, low CD4 count, low CD4/CD8 count, HIVRNA >50 copies/mL were independently associated with an increased risk of developing severe pneumonia (data not shown)." (PMID 27050752, 2016). "Among those hospitalized with pneumonia, use of HAART was associated with a reduced risk of death, independent of CD4 cell counts." (PMID 19750011, 2009). "We demonstrated that, in contrast to transient pneumonia with early bacterial clearance (“1x pna”), which failed to elicit strong antibody and T cell responses, persistent pneumonia (“4x pna”) strongly elicited S. aureus-specific antibodies and CD4+ T cells." (PMID 41050694, 2025). "Therefore, this study aimed to leverage the precision of CD4+ T cells count and the comprehensive nature of BALF-tNGS to delineate a quantitative and dynamic landscape of the pathogen profile in the BALF of patients with severe pneumonia." (PMID 41488483, 2025).
pneumonia (continued). "This may reflect pneumonia severity, or the large proportion of PLWH, the majority of whom were not on ART, as albumin levels in PLWH are lower pre-ART and correspond with weight and CD4 cell count." (PMID 40665761, 2025). "Indeed, persistent pneumonia and SSTI elicited strong toxin-specific antibody and CD4+ IL-17+ and IFNγ+ T cell responses, whereas transient pneumonia did not." (PMID 41050694, 2025). "Notably, we discovered that there is a striking increase in the frequency of memory T cells (CD44+CD62L-) while a dramatic decrease was observed in the population of naive T cells (CD44-CD62L+) in both CD4+ and CD8+ T cells of mice recovered from pneumonia compared to control mice." (PMID 37490715, 2023). "Taken together, these results demonstrate that, despite eliciting expansion of local CD4+ T cells following primary infection, pneumonia fails to prime expansion of memory Th17 and Th1 cells in the dLNs, and to a lesser extent than does SSTI in the spleen, upon recall by secondary pneumonia." (PMID 35983063, 2022). "The CD4 count was 3 cells/μL (reference: 200–3390 cells/μL) and the HIV RNA was 109,000 copies/mL (reference: not detected) Computed tomography of the chest revealed nodular opacities in both lower lobes with scattered areas of ground glass opacities consistent with pneumonia." (PMID 34941094, 2021). "Thus, the enhanced CD4-cell dependant IL-17 response to subsequent pneumonia in colonised mice does not seem to be required for protection in this model." (PMID 22003400, 2011). "In our model although colonisation results in a more rapid inflammatory response during early lung infection and a significant CD4-dependent IL-17 response, neither was necessary for the powerful protection against fulminant pneumonia provided by prior colonisation." (PMID 22003400, 2011). "However, in the multivariable Cox regression analysis, CD4 cell count, ART adherence level, WHO clinical staging, and initiation of ART within seven days of admission were significant predictors for the incidence of pneumonia among HIV-infected children on ART." (PMID 39232814, 2024). "A massive increase in CD4+ T cells and neutrophils was observed after the adoptive transfer of in vitro MDSCs; however, this change did not exacerbate pneumonia in the absence of poly(I:C), indicating that CD8+ T cells, monocytes, and NK cells may play roles in the exacerbation of pneumonia." (PMID 37818369, 2023). "We also observed a significant difference at the early time point in proliferative CD4+ and CD8+ T-cell responses between IC (but not TX) patients with pneumonia or mild symptoms." (PMID 34835067, 2021). "Depletion of CD4+ and CD8+ T cells during WCV priming does not affect bacterial burden or lung edema during acute pneumonia." (PMID 33199354, 2021). "In SARS-CoV-2 infected patients, both the counts of CD4 + cells and CD8+ cells in severe pneumonia patients were lower than non-severe patients." (PMID 32344708, 2020). "CD4 T cell counts showed no statistical differences among the four groups (IPF: 614.8 ± 469; CVD: 711.8 ± 431.1; CB/pneumonia: 403.3 ± 369.9; and PCP: 129 ± 96.7)." (PMID 19383170, 2009). "In multivariable analyses, younger age, alcohol use, lack of antiretroviral use, a lower CD4 cell count, and a higher HIV RNA were identified as independent predictors of pneumonia among all patients." (PMID 19340321, 2008). "Patients with Adv+ pneumonia showed a higher inhibition of T-cell immunity than did patients with Adv+ non-pneumonia, and counts of CD3+, CD4+, and CD8+ T-cells may predict the presence of pneumonia in Adv+ patients." (PMID 36161612, 2022). "Similarly, our data implied greater cellular immunosuppression in patients with Adv+ pneumonia, as demonstrated by a decline in counts of CD3+, CD4+, and CD8+ T-cells, than in patients with Adv+ non-pneumonia." (PMID 36161612, 2022).
pneumonia (continued). "Interestingly, CD4+ T lymphocyte counts recover rapidly, whereas CD8+ T lymphocyte cells in pneumonia patients did not recover at the 20th day, indicating that recovery of CD8+ T cell-mediated immunity needs a longer time." (PMID 33239109, 2020). "However, in the broader population of patients with severe pneumonia, including those with non-HIV-related immunosuppression, the dynamic relationship between CD4+ T cells count and the wider pathogen ecology has not yet been systematically investigated or elucidated." (PMID 41488483, 2025).
Hepatitis (186 papers, 1994 to 2026). Inflammation of the liver. "Some studies on complications associated with HIV infection have suggested that a CD4+ T-cell count <350 cells/μL can accelerate hepatitis progression and is a risk factor for malignancies and cervical cytological abnormalities in PLHIV." (PMID 40027893, 2025). "In the AIH model of ConA-induced hepatitis, CD4 T cells are the primary source of IL-22, and IL-22 deficiency has been reported to exacerbate hepatitis." (PMID 40616144, 2025). "The CD4 count has been linked to decreased humoral responses to several vaccines, including hepatitis A, hepatitis B, and pneumococcal vaccines, in PWLH (46, –, 48)." (PMID 40838719, 2025). "To illustrate the potential utility of restricted biomarkers, we compared the performance of CD27+ CD28+ CD4+ TEM frequency as a biomarker of hepatitis risk in our unrestricted and restricted datasets." (PMID 38926389, 2024). "Participants diagnosed with hepatitis or HIV-associated diagnoses had CD4 counts indicating impaired immune statuses." (PMID 39476279, 2024). "Using our restriction method, we identified CD27+ CD28+ CD4+ TEM cell frequency relative to CD4+ in blood as a biomarker of hepatitis risk after dataset restriction." (PMID 38926389, 2024). "Our example of CMV-associated expansion of CD4+ TEM cells predisposing to ICI-related hepatitis illustrates the influence of unanticipated variables over biomarker performance in heterogeneous populations." (PMID 38926389, 2024). "An association of an expanded CD4+ effector memory T cell (TEM) population with ICB-hepatitis was reported earlier." (PMID 36503532, 2022). "An expansion of effector-memory (TEM) CD4 T cells associated with antiviral immunity against herpesviridae was implicated in ICB-hepatitis." (PMID 36503532, 2022). "Secondly, a previous study has shown that activated and differentiated CD4 + T lymphocytes are recruited to the inflamed liver and cause liver inflammation." (PMID 36687701, 2022). "We previously reported that CD4+ TEM expansion in CMV-seropositive patients before therapy is a strong predictor of hepatitis risk after combined Nivolumab and Ipilimumab treatment." (PMID 36248910, 2022). "In short, we found no obvious clinical association to explain the predisposition of CD4+ TEM≥21% patients to hepatitis." (PMID 33664251, 2021). "The operators agreed in 39/40 (98%) of cases about the classification of patients’ hepatitis risk using the previously reported cut-off value of CD4+ TEM ≥ 16%." (PMID 34868015, 2021). "The scientific validity of measuring CD4+ TEM % as a risk-predictor for checkpoint blockade-related hepatitis was firmly established in our earlier studies." (PMID 34868015, 2021). "Opting for αPD-1 monotherapy or prophylactic valganciclovir in CMV IgG+ patients with unresectable metastatic disease and pre-treatment expansion of CD4+ TEM cells reduces their risk of hepatitis." (PMID 33664251, 2021). "Here, we identify a subset of patients predisposed to immune checkpoint blockade-related hepatitis who are distinguished by chronic expansion of effector memory CD4+ T cells (TEM cells)." (PMID 33664251, 2021). "The higher proportion of co-morbidity with other infections (e.g., Syphilis, Hepatitis) was associated with lower CD4 counts." (PMID 30822343, 2019). "Mutations in CD4+ Th epitopes (aa 1–20, 28–47, 50–69, 72–105, 108–165) are usually associated with immune evasion, minimum immune mediated hepatitis and viral persistence than CD8+ CTL epitopes." (PMID 25333524, 2014). "A potential role of CD4+ T cells in causing hepatitis has already been shown earlier, however the mechanism has never been elucidated." (PMID 21966366, 2011). "The risk of NVP–induced hepatitis was found to be increased 12-fold in women with greater than 250 CD4 cells/mm3." (PMID 20838641, 2010).